TIGIT (T cell immunoreceptor with Ig and ITIM domains)
Diseases named in the same sentence as TIGIT in open-access papers (continued):
Sharing a sentence is not in itself a finding about the gene and the disease.
tumor (continued). "SIGLEC15, PDCD1LG2(PD-L2), TIGIT, PDCD1(PD-1), CD274(PD-L1), CTLA4, LAG3, and HAVCR2(TIM3) are immunological checkpoints that perform a vital function in tumor immune evasion." (PMID 35840882, 2022). "Current studies reveal that TIGIT is expressed on activated CD8+ T cells, CD4+T cells, regulatory T (Treg) cells and NK cells, and can inhibit the anti-tumor responses mediated by immune cells." (PMID 35433470, 2022). "PDCD1, CD274, CTLA4, LAG3, TIGIT, and HAVCR2 are important immune checkpoints responsible for tumor immune escape." (PMID 35252356, 2022). "In vivo, BiPT-23 significantly suppressed tumor growth, by enhancing the infiltration of CD8+ T cells, NK cells, and depleting TIGIT+ Treg cells." (PMID 36289396, 2022). "For this purpose, surface molecules expressed at much higher levels on Tregs than T cells are used as targets, such as CD25, CTLA-4, GITR, 4-1BB, OX-40, LAG3, TIGIT, CCR4, and CCR8; tumor burden control has also been observed." (PMID 36159809, 2022). "Considering the complexity of TIGIT/CD155/DNAM-1, including sharing ligands, the prediction of the influence exerted by mAbs on the tumor blockade of TIGIT is challenging." (PMID 36497240, 2022). "We found that higher frequency of Treg and higher co‐expression of HLA‐DR, PD‐1, CD38, TIGIT, and CD45RO were correlated with tumor burden." (PMID 34165864, 2022). "Various cancers exhibit upregulation of CD155 and corresponding upregulation of NK and T cell expression of TIGIT and CD96 to evade anti-tumor immunity through inducing T cell or NK cell suppression." (PMID 35606854, 2022). "We constructed tumour models by injecting C57BL6 mice with WT (wild-type) U14, U14-NC-CD155 or U14-KO-CD155 cells to further verify the antitumor effects of targeting TIGIT/CD155 signalling in vivo." (PMID 35729552, 2022). "TIGIT was overexpressed in C4 /C9-CTLA CD4 T cell clusters, C5 and C6 /C4-GZMK CD8 T cell clusters, NSCLC tumor B cells, and suppressive tumor Tregs of CD4-C9CTLA cells vs. other tumor-infiltrating Tregs of CD4-C8-FOXP3 cells." (PMID 35804895, 2022). "At the same time, in order to investigate the relationship between type and immune checkpoints, we selected genes related to tumor immune checkpoints: PD-L1, CTLA4, LAG3, PDCD1, PDCD1LG2, and TIGIT." (PMID 36105091, 2022). "SIGLEC15, PDCD1LG2 (PD-L2), TIGIT, PDCD1 (PD-1), HAVCR2 (TIM3), CTLA4, LAG3, and CD274 (PD-L1) are transcripts related to immunological checkpoints that have a function in tumor immune evasion." (PMID 36042287, 2022). "In contrast, TIGIT and CD96 are inhibitory receptors, and PVR upregulation in heterogeneous tumor cells results in tumor cell recognition and binding by activating receptor CD226 and the inhibitory receptors TIGIT and CD96." (PMID 35625835, 2022). "It is well known that in the field of tumour immunotherapy, five immune checkpoints, namely, PD-1, CTLA-4, Tim-3, LAG-3, and TIGIT, have inhibitory effects on T-cell proliferation." (PMID 36110204, 2022). "At present, immune checkpoints including PD-L1, CTLA-4, LAG3, TIGIT and TIM-3, are thought to contribute to tumor immune escape." (PMID 35665772, 2022). "TIGIT can also upregulate the expression of the chemokine CCL4 and the chemokine receptor CCR8, which help with Treg migration and retention in tumor tissue." (PMID 35008385, 2022). "TIGIT has been reported to be coexpressed with PD-1 on tumor-antigen specific CD8+ T cells and CD8+ tumor-infiltrating lymphocytes (TIL) in human cancers." (PMID 35154317, 2022). "SIGLEC15, PDCD1LG2(PD-L2), TIGIT, PDCD1(PD-1), CD274(PD-L1), CTLA4, LAG3, and HAVCR2(TIM3) are transcripts related to immunological checkpoints that perform vital functions in tumor immune evasion." (PMID 36253777, 2022). "TIGIT and TIM-3 seem to have similar biological characteristics, the expression of TIGIT in tumor cells is also high, accounting for 45.4%, and the expression of TIGIT and TIM-3 proteins in TILs and tumor cells display correlated." (PMID 36561512, 2022).
tumor (continued). "Antibody blockade of TIGIT enhances antitumor CD8+ T cell response and prompts tumor regression in a colorectal cancer (CRC) mouse model." (PMID 35164813, 2022). "We investigated the levels of tumor-infiltrating B cells, T cells and NK cells compared to normal tissue milieu and established the expression profiles of PD-1, TIM-3, LAG-3, TIGIT, and ICOS on the different tumor-resident lymphoid populations." (PMID 33477864, 2021). "Eight tumor-related immunosuppressive molecules, CD274, CTLA4, HAVCR2, LAG3, PDCD1 (PD1), PDCD1LG2, SIGLEC15, and TIGIT, had higher expression in HNSCC tumor tissues compared with HNSCC normal tissues." (PMID 34917682, 2021). "We previously demonstrated that F. nucleatum binds and activates the human inhibitory receptors TIGIT and CEACAM1 leading to inhibition of T and NK cell anti-tumor immunity." (PMID 34395310, 2021). "TIGIT has been reported as marker for CD8+ T-cell exhaustion and is also a characteristic marker for Tregs in the tumor microenvironment." (PMID 34572463, 2021). "Using this same Treg gating strategy, we next examined the surface expression of eight protein markers (CD30, OX40, 4-1BB, TIGIT, PD-L1, IL-1R2, IL-21R, and CCR8) on tumor-infiltrating Tregs of five CRC patients from our South-East Asian cohort." (PMID 33527196, 2021). "TIGIT is a co-inhibitory receptor that emerged as ICI candidate because it is over-expressed on exhausted TINK and tumor-infiltrating T cells and is responsible for such functional exhaustion." (PMID 34394116, 2021). "In contrast to TIGIT, CD155 was exclusively expressed by the tumor epithelium with a foremost moderate to strong membranous immunoreactivity." (PMID 33918309, 2021). "PD-1, TIGIT, and CD96 can negatively affect NK cell function, and targeting these receptors with immune checkpoint inhibitors was found to enhance the anti-tumor response both in vitro and in vivo." (PMID 33572396, 2021). "Co-inhibitory TIGIT and CD96 compete with co-stimulatory CD226 for their ligands CD155 and CD112 on dendritic cells (DCs) or tumor cells to suppress the anti-tumor immunity of TILs." (PMID 34858835, 2021). "To evaluate the potential of blockage of the TIGIT/CD155 axis for GBC, we quantified the expression levels on tumor cells and TILs by immunohistochemistry." (PMID 33918309, 2021). "Tumor-infiltrating Tregs (TI-Tregs) express immune checkpoint molecules such as CTLA-4, PD-1, TIM-3, LAG3, and TIGIT." (PMID 33598101, 2021). "Ligation of TIGIT with its ligands CD155 and CD112, expressed on tumor and myeloid cells, promotes NK and T cell tolerance." (PMID 34439292, 2021). "In BRCA, the expression of PVRL1/CD111, PVRL2/CD112, TIGIT, and DNAM-1/CD226 in tumor tissues was significantly higher than that in normal tissues, but PVRL3/CD113 showed an opposite expression pattern." (PMID 33581644, 2021). "Our data confirm that TIGIT is frequently expressed in T lymphocytes within the tumor microenvironment of CHL8 and TIGIT expression seems to be related to CD4+ activated T lymphocytes surrounding the malignant HRS cells." (PMID 33782477, 2021). "An interrogation of the expression pattern of the ligands to TIGIT and ICOS has shown distribution across different cellular compartments, which were significantly elevated in the tumour compared to the normal pancreas." (PMID 33917832, 2021). "The co-inhibitory receptors CD96, TIGIT, PVRIG and the costimulatory receptor CD226 comprise a critical regulatory system for lymphocyte activity and anti-tumor immunity, and they share the same ligands CD155 and PVRL2." (PMID 34174928, 2021). "The tumor stroma of CCA patients showed infiltration of lymphocytes expressing ICs, including PD1 and TIGIT." (PMID 34069452, 2021). "In hypoxia status, tumor cells inhibited immune cells’ antitumor ability by interacting with inhibitory receptors in immune cells like PDCD1, TIGIT, and LILRB or weakening the immune-stimulation ligand–receptor interactions such as CCL, TNF, and FASLG." (PMID 34956900, 2021).
tumor (continued). "IBI939 can directly bind to TIGIT, disturb the interaction between CD155 and TIGIT, relieve the inhibition and depletion of T cells and NK cells and enhance the anti-tumor immune response of T cells and NK cells." (PMID 33672017, 2021). "Although the effect of azelnidipine for dual blocking of CD47/SIRPα and TIGIT/PVR interactions indeed occurs within one single model, it is hard to distinguish the contribution to the anti-tumor effects of either single blockade." (PMID 34068552, 2021). "Next, we compared the levels of tumor-infiltrating B cells, T cells and their subsets, and NK cells expressing PD-1, TIM-3, LAG-3, TIGIT, and ICOS between patients with advanced and early stage CRC." (PMID 33477864, 2021). "TIGIT (T cell immunoreceptor with Ig and ITIM domains) expression is upregulated in tumor infiltrating CD8 lymphocytes with exhausted phenotype according to reduced immune signaling." (PMID 34722633, 2021). "In summary, in this study we show that PD-L1 is upregulated in tumor and immune cells in a subset of Western GBC in late tumorigenesis and provide evidence for TIGIT/CD155 axis as a new immune checkpoint for complement therapy in GBC." (PMID 33918309, 2021). "The delayed treatment of GPR171 antagonist or TIGIT mAb alone had minimal effects on slowing down tumor progression; however, GPR171 antagonist displayed a great synergy with anti-TIGIT to inhibit CT26 tumor growth, so as to extend mouse survival." (PMID 34615877, 2021). "Previous studies have demonstrated that engagement of TIGIT with CD155 can deliver an inhibitory signal, leading to increased secretion of IL-10 in tumor cells and dendritic cells (DCs)." (PMID 33581644, 2021). "Novel ICBs such as anti-TIM-3, anti-TIGIT, or anti-LAG-3 were also shown to restore the function of tumor-infiltrating T cells in vitro, and they are now under the early stage of clinical trials." (PMID 34575463, 2021). "Researchers showed that blockade of TIGIT along with PD-L1 enhanced CD8+ T-cell effector function and tumor and viral clearance." (PMID 34572463, 2021). "In COAD and READ, the expression of PVR/CD155, PVRL1/CD111, PVRL2/CD112, TIGIT, and PVRIG/CD112R was significantly higher in tumor tissues than that in normal tissues." (PMID 33581644, 2021). "It was noticed that the percentage of CD3+TIGIT+ T(53.89 ± 14.05), CD4+TIGIT+ T(54.88 ± 18.56) and CD8+TIGIT+ T cells (52.03 ± 7.65) were significantly increased in tumor tissues when compared with peripheral blood samples." (PMID 34659197, 2021). "In a study of 10 fresh tumor samples from untreated TNBC patients, TIGIT overexpression was found in CD8+ and CD4+ TILs, and highly expressed TIGIT and its ligands (CD155 and CD112) were discovered in tumor cells and antigen-presenting cells." (PMID 33717059, 2021). "Both HLA class 1/2 and immune checkpoint ligands for TIM-3 (e.g., HMGB) and TIGIT (e.g., PVR and PVRL2) were highly expressed by most tumours." (PMID 34503115, 2021). "To validate the role of the TIGIT/CD155 axis in the resistance mechanism of MEL04, we performed an IFN-γ release functional assay using pairs of autologous tumor cell lines and TILs from the same patients." (PMID 34795004, 2021). "TIGIT binds to CD155 or CD112 on the surface of tumour cells and antigen presenting cells in tumour microenvironment." (PMID 34841705, 2021). "We further investigated the anti-tumor effects of azelnidipine in a CT26 model, which is widely used for CD47/SIRPα and TIGIT/PVR blockade therapy and the exploration of the T cell immune response." (PMID 34068552, 2021). "TIGIT expression impairs T/NK cells via binding to CD155 (PVR) and CD112 (Nectin2) expressed in myeloid cells and tumor cells." (PMID 33535613, 2021). "The interaction between TIGIT and CD155/PVRL2 suppresses anti-tumor and anti-viral immune responses in both direct and indirect manners." (PMID 34174928, 2021).
tumor (continued). "Other genes and signatures that were correlated with longer OS include Treg, TIGIT (T cell immunoreceptor with Ig and ITIM domains), PD-1, MAGEs (melanoma antigen genes), NK cells, MHC2, B cells, and tumor inflammation signature (TIS) (p < 0.05)." (PMID 33428680, 2021). "Therefore, the immune checkpoint blockade targeting TIGIT enables a highly powerful T-cell antitumor response in several ways, by restoring the antitumor potential of T effector cells, dampening the Treg immunosuppressive effect, and diminishing the tumor-supporting effects of Tfh cells in FL." (PMID 34069564, 2021). "To verify our guess, we investigated tumor-related immune checkpoints, including CD273, CD274, CTLA-4, and the ones that were newly emerging, LAG-3, TIM-3, TIGIT, CD276, BTLA, and IDO1, between the two subgroups." (PMID 33558879, 2021). "Relative to the primary tumour, even-higher levels of three checkpoints—LAG3, TIGIT and HAVCR2—were expressed on MANA-specific TIL in the metastasis." (PMID 34290408, 2021). "It was demonstrated that dual PD-1/TIGIT blockade potently increases tumor antigen-specific CD8+ T cell expansion and function in vitro and promotes tumor rejection in mouse tumor models leading to a cure rate up to 100%." (PMID 34102454, 2021). "TIGIT binds with high-affinity to CD155 (PVR) and with low-affinity to CD112 (PVRL2; nectin-2) which are expressed in the tumor microenvironment (TME) by antigen presenting cells (APCs) and tumor cells." (PMID 34025646, 2021). "Accordingly, addition of anti-TIGIT mAb increased the proportion of effector memory CD8+ T cells, as well as cytokine production in tumor-infiltrating CD8+ T cells." (PMID 34795004, 2021). "Surviving tumor cells and TILs after coculture had higher CD155 and TIGIT expression than the controls." (PMID 34795004, 2021). "Regulatory T cells were almost exclusively found in tumor tissue samples and expressed inhibitory molecules such as CTLA4 and TIGIT (arrowheads) corresponding to their immunosuppressive role." (PMID 34663877, 2021). "In terms of LUAD patients, most biomarkers, including IDO1, CTLA4, LAG3, CD40, TNFRSF18, TIGIT, and TNFSF14, were significantly increased in tumor tissues with high B cell abundance compared with that of low B cell group." (PMID 34422829, 2021). "TIGIT is expressed in both T cells and NK cells and inhibits immune response mediated via triggering CD155 on tumor cells." (PMID 34869309, 2021). "To examine if tumor-infiltrating MAIT cells have an exhausted phenotype, we analyzed their expression of the surface markers PD-1, Tim-3, CD39, TIGIT, BTLA, and LAG3, which have all been used to identify exhausted conventional CD8+ T cells in tumors." (PMID 33885944, 2021). "Dual blockade of TIGIT and either TIM-3 or PD-1 has revealed an anti-tumor mechanism through immune cell proliferation, cytokine release and reversal of T cell exhaustion." (PMID 34268109, 2021). "They identified a subset of TIGIT+ cells with the high-plasticity cell state (HPCS) and annotated these cells as transitioning tumor cells that contributed to tumor progression and chemoresistance." (PMID 34177965, 2021). "TIGIT competes with its opposing receptor CD226 for its ligands, the latter receptor enforcing anti-tumor responses through NK and T cell activation." (PMID 34439292, 2021). "NK–tumor interactions included HLA-C/KIR2DL4, HLA-E/CD94 (KLD1), TIM3 (HAVCR2)/Galectin-9, CD96-PVR/Nectin1 and TIGIT-PVR/Nectin2." (PMID 33671917, 2021). "The CD226 activating receptor and the TIGIT and CD96 inhibitory receptors have been shown to be key regulators of anti-tumor immune responses by NK cells." (PMID 34367161, 2021). "Studies have shown that the expression of immune checkpoints such as PD-1L, TIM3, TIGIT, and CTLA4 can affect tumor progression and thus change patient prognosis." (PMID 34484330, 2021).
tumor (continued). "Analysis of tumor and tumor adjacent tissue further revealed that CD163+ macrophages and TIGIT+ Tregs were enriched in HCC tissue, while cytotoxic CD8+ T cells and NKT cells were enriched in tumor adjacent tissue independent of HBV status." (PMID 34771611, 2021). "Antibody double-blocking of TIGIT/PVR and programmed cell death protein 1 (PD-1)/programmed death-ligand 1 (PD-L1) has been demonstrated to produce synergistic effects in both tumor models and clinical trials." (PMID 34367994, 2021). "TIGIT is a co-inhibitory receptor expressed in lymphocytes, particularly in effector and regulatory CD4+ T cells, and in tumor cells." (PMID 33804419, 2021). "Studies have shown that tumor-infiltrating lymphocytes have elevated levels of TIGIT co-expressed with PD-1, LAG-3 and TIM-3 suggesting a role in tumor progression." (PMID 34268109, 2021). "In prostate cancer patients, CD112R is highly expressed on tumor-infiltrating NK cells, and, in endometrial cancer, CD112R and TIGIT are co-expressed on NK cells." (PMID 34503073, 2021). "In recent years, it has been shown that tissue-resident T lymphocytes can overexpress PD-1 and other immune checkpoint molecules, such as TIGIT, LAG-3, and Tim-3, in some experimental animal and human tumor tissues." (PMID 35096624, 2021). "DUSP12 expression was positively correlated with the abundance of tumor-infiltrating CD4+ T cells, macrophages, neutrophils, dendritic cells, and expression of the immune-checkpoint moieties HARVC2, TIGIT, CTLA4 and PDCD1." (PMID 34414037, 2021). "Engagement of CD226 with its ligands PVRL2 and CD155 on target cells is essential for enhancing the anti-viral and anti-tumor functions of NK cells and T cells, whereas CD96, TIGIT and PVRIG counterbalance CD226-dependent lymphocyte activation." (PMID 34174928, 2021). "NEFM negatively correlated with PVR (CD155), an immune checkpoint on tumor cells and interacting with CD96, CD226, and TIGIT (T cell immune receptor with immunoglobulin and ITIM domains) on TILs to modulate immune function in tumor microenvironment." (PMID 34001208, 2021). "Few NK cells are detected in endometrial tumors and tumor-resident CD103+ NK cells express more co-inhibitory molecules, such as TIGIT and TIM3, depending on the severity of the disease." (PMID 34177887, 2021). "Tumor cells produce soluble molecules, such as IDO, PEG2, TGF-β, and a series of membrane molecules, including PD1, PD-L1, LAG3, TIGIT, and CTLA4." (PMID 34177887, 2021). "Two major ligands for TIGIT are poliovirus receptor (PVR, CD155) and poliovirus receptor-related 2 (PVRL2, CD112, nectin-2), which are expressed by tumor cells as well as myeloid cells." (PMID 33581644, 2021). "T cell-specific PCPB1 deletion in mouse tumor models caused Treg differentiation and the induction of multiple checkpoint molecules including PD-1, TIGIT, and VISTA on tumor-infiltrating lymphocytes and reduced anti-tumor immunity." (PMID 34948104, 2021). "The best overall response rate and progression-free survival (PFS) were analyzed depending on the expression of CD68, CD163, PD-1, LAG-3, TIM-3, CTLA-4, TIGIT, CD163/c-maf in the tumor microenvironment in primary and sequential biopsies." (PMID 34830831, 2021). "We found that TOX and potentially TIM-3, CTLA-4, VISTA, TIGIT, KLRG1, TOX2, SIRT1, Ki-67, and Helios mRNA levels in tumor tissue were elevated in advanced disease stages, suggesting their potential roles in CRC progression." (PMID 32393998, 2020). "While DNAM-1+ tumor-infiltrating lymphocytes were also observed at higher levels than in normal brain tissue, DNAM-1 was typically co-expressed with TIGIT, likely disrupting DNAM-1 homodimerization and rendering DNAM-1 nonfunctional." (PMID 32532329, 2020). "We found that mRNA levels of PD-1, TIM-3, CTLA-4, TIGIT, CD160, CD244, and KLRG1 were elevated in CRC tumor tissue, implicating their potential contribution to CRC development and/or progression." (PMID 32393998, 2020).